EGFR (epidermal growth factor receptor)
Diseases named in the same sentence as EGFR in open-access papers (continued):
Sharing a sentence is not in itself a finding about the gene and the disease.
metastatic disease (continued). "For example, EGFR, epidermal growth factor receptor, was overexpressed in the majority of clear-cell renal cell carcinoma and co-overexpression of EGFR and erbB-2 gene was associated with metastatic disease." (PMID 34335688, 2021). "Using ctDNA, 62.5% of patients were identified with EGFR mutations (exon 19 deletion, exon 20 T790 M insertion and exon 21 L858R mutation) at the baseline, while the rate of EGFR mutation positivity was higher among patients with metastatic disease." (PMID 35127511, 2021). "Among the 16 EGFR-mutated patients with progressive disease, 4 had local tumor progression and 12 had metastatic disease." (PMID 34696229, 2021). "On the other hand, high EGFR expression levels in either primary tumors or metastatic tissues were associated with multiple metastatic disease." (PMID 32155907, 2020). "The most common sites of distant metastatic disease in the EGFR-mutated group included the lung (n = 18; 58%), pleura (n = 10; 32%), and brain (n = 8; 26%)." (PMID 32523650, 2020). "Among cases of metastatic disease recurrence, only a minority of cases in both groups were limited to lung-only recurrence (26% and 14% in EGFR-mutated and wildtype disease, respectively, p = 0.51)." (PMID 32523650, 2020). "These sites of micro-metastatic disease in EGFR-mutated tumors likely represents a more systemic disease process in contrast to more localized disease process or field cancerization found in EGFR-wildtype disease." (PMID 32523650, 2020). "In summary, this study suggests EGFR mutation as an important marker for predicting metastatic disease recurrence and highlights the growing need for precision medicine in early and locally advanced NSCLC." (PMID 32523650, 2020). "Our team is currently looking for correlations between primary and/or metastatic tumor size, EGFR mutations in plasma, and disease progression." (PMID 33266057, 2020). "Fluorescence molecular imaging using an anti-EGFR contrast agent can identify LNs at risk of harboring metastatic disease." (PMID 31695030, 2019). "Because the responsiveness to EGFR tyrosine kinase inhibitors tends to correlate with the EGFR mutation status in metastatic lesions compared with primary tumors, metastatic tumors should be retested." (PMID 31455365, 2019). "Current research is focusing on both KRAS and BRAF as predictive and diagnostic biomarkers in patients with metastatic disease treated with anti-EGFR therapies, such as panitumumab and cetuximab." (PMID 28097409, 2017). "Discordances between primary tumours and corresponding metastatic tumours in terms of EGFR mutation status are extremely rare." (PMID 28832323, 2017). "For pancreatic adenocarcinoma, EGFR expression levels reported in different series have ranged from 25% to 90%, and EGFR expression has been shown to be associated with advanced stage, metastatic disease, and poor differentiation and survival." (PMID 27399694, 2016). "Two studies included in this review presented results related to EGFR mutation heterogeneity in matched primary and metastatic tumour samples." (PMID 26338018, 2015). "The 26 discordant results were EGFR mutation-positive in their metastatic tumour only; these were reanalysed using the ARMS method, which indicated that 10/26 (38 %) of these were in fact concordant." (PMID 26338018, 2015). "EGFR mutations in both primary and metastatic tumours were also found to be linked to response to EGFR TKI therapy." (PMID 26338018, 2015). "Two of the discordant cases resulted from a different EGFR mutation being present in the primary versus metastatic tumour (E746-A750 vs L747-T751 and L747-P753insS vs R748-P752, respectively)." (PMID 26338018, 2015).
metastatic disease (continued). "Most, but not all, studies included in this review reported that where both primary and corresponding metastatic tumours were EGFR mutation-positive prior to any therapy, the same mutation subtype was observed." (PMID 26338018, 2015). "Overall, 54/56 (96 %) and 25/30 (83 %) primary and metastatic tumour sites were EGFR mutation-positive, respectively." (PMID 26338018, 2015). "The EGFR mutation ratios detected in different sites of primary tumors were highly concordant, whereas the EGFR mutation ratios in metastatic tumors were lower than those in primary tumors." (PMID 24398248, 2014). "The growth factor control of cell fate is a pivotal step in cancer progression; indeed, the high expression of epidermal growth factor receptor (EGFR) in cancers has been associated with metastatic tumors and poor clinical outcomes." (PMID 24906407, 2014). "If metastatic tumors are used for the detection of EGFR mutation, the sensitivity of the detection assay must be considered." (PMID 24398248, 2014). "EGFR mutation status and abundance were compared among different areas of a primary tumor and its corresponding metastatic tumor of the same individual." (PMID 24398248, 2014). "In primary tumors lacking KRAS, NRAS, or BRAF mutations, we did identify occult alterations in the EGFR/RAS pathway that in some patients were private to the metastatic tumor." (PMID 25164765, 2014). "If metastatic tumors are used for EGFR mutation detection, the sensitivity of the detection assay must be taken into consideration." (PMID 24398248, 2014). "In this study, we used real-time PCR to quantitatively detect EGFR mutations in primary and metastatic tumors." (PMID 24398248, 2014). "We did not detect any discordance for the mutation findings, as both primary and metastatic tumor from the first two cases had the EGFR exon 19 deletions." (PMID 24171005, 2013). "We analyzed the EGFR mutation status in 67 paired tissues samples (primary and metastatic tumors) using the Scorpion Amplified Refractory Mutation System assay, a 27% of discordant rate was found." (PMID 24212826, 2011). "The aim of this study is to determine the discordance of EGFR mutations between primary and corresponding metastatic tumors in non-small cell lung cancer (NSCLC)." (PMID 21645456, 2011). "Discordance in the mutation status of the EGFR gene in the primary tumor and corresponding metastatic tumor is occasionally observed." (PMID 22108465, 2011). "TOPK expression is an unfavourable prognostic indicator in sporadic patients with KRAS or BRAF mutations and also in patients with metastatic disease experiencing a response to anti-EGFR therapies." (PMID 19935791, 2010). "In conclusion, TOPK seems to be a valuable prognostic factor in patients with sporadic CRC with KRAS or BRAF gene mutations, as well as in patients with metastatic disease who respond to anti-EGFR therapies." (PMID 19935791, 2010). "Epidermal growth factor receptor mutations were detected in the metastatic tumours of three (12%) patients." (PMID 19238633, 2008). "(v) For metastatic tumors with EGFR T790M mutation that have progressed on other EGFR-TKIs." (PMID 40940888, 2025). "The current platform could be used to follow possible residual or recurrent GBM and other cancers with amplified aEGFR and tEGFR, as the presence of amplification/mutation of EGFR is frequently retained in metastatic disease." (PMID 38830977, 2024). "Several EGFR-TKIs have been approved for the first-line treatment of patients with metastatic disease and EGFR-activating mutations (exon 19 deletion, L858R), including osimertinib (the preferred option in most guidelines), gefitinib, erlotinib, afatinib and dacomitinib." (PMID 36571695, 2023). "Consequently, using plasma samples from patients with advanced or metastatic tumors instead of early-stage tumors is recommended to confirm the positivity rate of EGFR mutations in EGFR-LAMP liquid biopsy." (PMID 35744511, 2022).
metastatic disease (continued). "In addition, high-grade PDAC cell lines depict EGFR upregulation, which has been associated with advanced stage, metastatic disease, and poor differentiation and survival in pancreatic adenocarcinoma." (PMID 32848164, 2020). "Additional large observational cohort studies are needed to help determine whether the more systemic nature of EGFR-mutated tumors affects sites of metastatic disease at time of first recurrence." (PMID 32523650, 2020). "Only the minor allele of rs2070600 was associated with a higher NLR (β = 0.209, p = 0.043) and a poor prognosis (Hazard ratio = 2.06, 95% Confidence interval = 1.09–3.77, p = 0.028) in patients with metastatic disease, independently of background characteristics, including EGFR mutation status." (PMID 29212235, 2017). "Notably, CCT365623 and BAPN elicit a significant reduction in MATN2 protein levels in both the primary and metastatic lung tumours and this is accompanied by the loss of EGFR from the plasma membranes of the cells in both the primary and metastatic tumours." (PMID 28416796, 2017). "However, some evidence showed that the presence of EML4-ALK gene rearrangement is associated with EGFR-TKIs resistance among patients with metastatic diseases." (PMID 27791985, 2017). "Finally, we identified a population with KRAS‐mutated metastatic tumors that received treatment with EGFR antibodies prior to biopsy of metastatic site, based on a diagnosis of KRAS wild‐type in CRC primary performed outside our institution." (PMID 28618197, 2017). "Moreover, the previous findings that resistance to EGFR monoclonal antibody therapies in patients with metastatic tumors is mediated by Ras mutation has further increased the importance of controlling both EGFR- and oncogenic Ras-mediated signaling." (PMID 26384305, 2015). "EGFR mutation ratios in primary and metastatic tumors are different." (PMID 24398248, 2014). "EGFR mutation ratios in primary tumors and metastatic tumors are different." (PMID 24398248, 2014). "However, several other studies have observed heterogeneity in EGFR gene expression, mutation or amplification between primary and metastatic tumors or among intra-tumoral foci, with different discordance rate." (PMID 23520442, 2013). "In summary, the substantial discordance of KRAS and EGFR mutation status between primary tumors and metastatic tumors may have therapeutic implications for EGFR-targeted therapy strategy." (PMID 21414214, 2011). "For NSCLC patients with metastases, determining the KRAS and EGFR mutation status in both primary and metastatic tumors may be critical for making meaningful decisions regarding the appropriate use of targeted therapies." (PMID 21414214, 2011). "The first-line treatment with inhibitors of epidermal growth factor receptor (EGFR) could be considered for the treatment of EGFR mutated patients with metastatic disease." (PMID 20433767, 2010). "Other explored variables, including gender, site of metastatic disease, the extent of metastatic disease, previous resection of the bowel cancer primary, and the number of lines of therapy did not have a significant influence on the benefit associated with EGFR mAb in patients in KRAS WT mCRC." (PMID 38402342, 2024). "Furthermore, within the ALK-positive cohorts, 6 (42.9%) of 14 patients had stage IV disease, but only 10 (10.2%) of 98 patients with EGFR mutations had metastatic disease, which suggests a trend toward higher clinical stage among ALK-positive patients compared with EGFR mutant cohorts (P = 0.002)." (PMID 34234236, 2021). "Afatinib is an irreversible second generation pan-ErbB inhibitor developed as a first-line treatment of patients with metastatic NSCLC whose tumors harbor EGFR mutations or deletions as well as in patients with metastatic disease that progressed after platinum-based chemotherapy." (PMID 28418845, 2017).
metastatic disease (continued). "Then, NPOT analysis of panitumumab interactome in metastatic versus non‐metastatic tumors demonstrated that EGFR was exclusively present in metastatic tumors, suggesting a distinct EGFR‐driven signaling landscape in advanced CRC." (PMID 41319168, 2025). "Comparable to EGFR mutations, BRAF mutations are associated with a higher rate of metastatic disease to the CNS in NSCLC." (PMID 40075878, 2025). "Systemic chemotherapy, such as a combination of cisplatin with 5-fluorouracil, carboplatin, or EGFR inhibitors, is typically employed as adjuvant therapy or for treating locally advanced, inoperable, or metastatic disease." (PMID 40250184, 2025). "The model included five factors: de novo metastatic disease at presentation, response to EGFR-TKI, ECOG performance status, and treatment line of EGFR-TKI." (PMID 40805260, 2025). "Positive EGFR mutations, KRAS mutations, and EML4::ALK fusion in metastatic tumors often suggest a lung origin." (PMID 39980562, 2025). "Synchronous oligometastatic disease, oligo-residual disease, or poly-metastatic disease can potentially develop into Oligo-PD after treatment with EGFR-TKIs or LAT." (PMID 40647500, 2025). "As an example of the importance of analyzing the molecular profile of metastatic disease is the use of EGFR inhibitors, which are effective in a subset of wild-type allRAS RCC." (PMID 39936820, 2025). "In conclusion, additional studies will be required to prove a real benefit related to the administration of drugs targeting EGFR in ESCC patients with advanced or metastatic disease." (PMID 36661697, 2023). "A significant proportion of laboratories (79%) reported conducting reflex EGFR testing, which increased to 90% when laboratories were aware of advanced or metastatic tumour stage." (PMID 37713929, 2023). "Only first-generation EGFR-targeting therapies were approved for the treatment of metastatic disease at the time of the study." (PMID 37040387, 2023). "The EGFR inhibitor, cetuximab, is being studied in combination with an IL-15 receptor agonist in advanced or metastatic disease." (PMID 38063578, 2023). "In recurrent or metastatic disease, platinum-based chemotherapy or targeted therapy against epidermal growth factor receptor (EGFR) with cetuximab can be utilized." (PMID 37444461, 2023). "We, however, measured RTKs in metastatic tumours, and there is some evidence that these tumours lose the expression of RTKs as described in an immunohistochemistry study showing that EGFR is lost in metastatic CRC cancer." (PMID 36890818, 2023). "EGFR (epidermal growth factor receptor) regulates epithelial cell growth and is overexpressed in various metastatic tumors." (PMID 37371090, 2023). "Nuclear EGFR (nEGFR) correlates with metastatic disease and worse patient prognosis yet targeting its nuclear localization has proved difficult." (PMID 37720348, 2023). "In our previous study, IHC of metastatic tumors showed that the percentage of tumors positive for EGFR was higher, and those positive for PTEN and TLE3 were lower in QNBCs compared to TNBCs." (PMID 36550153, 2022). "The monoclonal antibody Cetuximab directed against epidermal growth factor receptor (EGFR) is used alone or in combination with chemotherapy, for the treatment of patients with recurrent or metastatic disease." (PMID 36341402, 2022). "Patients with recurrent/metastatic disease undergo combination chemotherapy containing cetuximab, the monoclonal antibody used against the epidermal growth factor receptor (EGFR)." (PMID 35626010, 2022). "Clinical studies identified the increased activation of Akt, overexpression of EGFR and the presence of active nuclear IκKβ as predictors of aggressive and metastatic disease." (PMID 35666359, 2022). "In another series of 21 primary UMs tested, EGFR was detected in 6 of them and was found to correlate with metastatic disease." (PMID 35781872, 2022).
metastatic disease (continued). "Reflex testing for EGFR at the time of the advanced/metastatic disease diagnosis was performed in half of the participating sites (n = 13; 52%), and reflex T790M mutation testing at the time of progression in one third of sites (n = 9; 36%)." (PMID 36005198, 2022). "An analysis of activated RTKs in TH tumor lysates revealed a striking dichotomy between localized and metastatic tumors with a switch from EGFR to activated TYRO3 in 57% of metastatic cases." (PMID 36230684, 2022). "Several randomized trials have defined the role for SBRT in the treatment of metastatic EGFR-mutated NSCLC, especially in those with limited metastatic disease burden." (PMID 36010982, 2022). "In the clinic, anti-epidermal growth factor receptor (EGFR)-based therapies are frequently used to treat CRC patients with metastatic disease if the tumors are wild-type (WT) KRAS." (PMID 35279145, 2022). "So far, only a few therapeutic agents have shown efficacy in metastatic disease: fluoropyrimidines, oxaliplatin, irinotecan, anti-epidermal growth factor receptor (anti-EGFR) drugs as cetuximab and panitumumab, and anti-angiogenic drugs." (PMID 35761123, 2022). "Additional biomarkers for aggressive and metastatic disease include the indicators of increased signalling of two additional pillars, the overexpression of EGFR and the presence of active nuclear IκKβ." (PMID 35666359, 2022). "Prior studies suggest CMS1 class to be least responsive to EGFR inhibitor therapy, especially among the metastatic tumors where it was noted to have the worst prognosis." (PMID 34771559, 2021). "Basal level of phospho-EGFR upon CPAP depletion was found to be profoundly higher in mesenchymal cell-line UM-SCC-74B which was derived from a recurrent metastatic tumor and in an OSCC cell-line with epithelial phenotype (SCC-Cal27)." (PMID 33889303, 2021). "Median OS from the time of diagnosis of metastatic disease was 23.5 months (95% CI: 16.9–30.1) and median OS from the initiation of EGFR-TKI was 20.6 months (95% CI: 13.5–27.6)." (PMID 34940073, 2021). "As compared with the primary tumors, organoids derived from metastatic tumors show a higher frequency of resistance to the microtubule‐ and EGFR‐targeting drugs." (PMID 34605222, 2021). "EGFR was found to be highly expressed in local recurrent tumors (≥grade 2, 32/42, 76.2%) and metastatic tumors (≥grade 2, 64/90, 71.1%)." (PMID 34204797, 2021). "Currently, k-Ras (KRAS) mutation testing is recommended for CRC patients with advanced metastatic disease in order to predict the resistance to epidermal growth factor receptor (EGFR)-targeting therapy." (PMID 33805921, 2021). "In late stage metastatic disease, chemotherapy is performed together with targeted therapies, mainly aiming at the epidermal growth factor receptor (EGFR) and vascular endothelial growth factor (VEGF)." (PMID 32610612, 2020). "Conversely, MLH1, PMS2, CEA and EGFR expression was markedly more common in, and in same cases exclusive to, liver metastatic tumors." (PMID 32170146, 2020). "With tumor molecular genetics at the forefront of precision medicine, subclassification of NSCLC based on EGFR mutation status has been paramount for predicting response to EGFR targeted therapies in unresectable advanced and metastatic disease." (PMID 32523650, 2020). "Analysis of primary and brain-metastatic tumor specimens from patients with NSCLC indicated that BASP1-positive samples also had strong EGFR staining." (PMID 33042262, 2020). "We compared the EGFR H-score of the primary tumors with different metastatic potentials (i.e., single versus multiple metastatic diseases) and we found that EGFR protein expression is significantly higher in primary tumors with multiple metastases (p = 0.007)." (PMID 32155907, 2020). "The median EGFR-HS was similar in both the primary and the metastatic tumor tissues (100 ± 66 versus 110 ± 75, respectively)." (PMID 32155907, 2020).